HLA-DRB1 (major histocompatibility complex, class II, DR beta 1)
Diseases named in the same sentence as HLA-DRB1 in open-access papers (continued):
Sharing a sentence is not in itself a finding about the gene and the disease.
autoimmune disease (continued). "There is increasing evidence that the lower methylation (hypomethylation) of HLA-DRB1 gene promoter, leading to HLA-DRB1 overexpression, is associated with a higher risk of developing various autoimmune diseases." (PMID 32370106, 2020). "The DRβGln70 amino acid residue is associated with AAA and it forms together with amino acid residues in positions 67, 71 and 74 a binding peptide pocket (#4) in HLA-DRB1, which is associated with certain autoimmune disorders." (PMID 31310631, 2019). "Significantly associated residues across eleven autoimmune diseases within the peptide-binding groove of HLA-DRB1." (PMID 31022184, 2019). "The β71 position within the P4 pocket of HLA-DRB1 has previously been implicated in the pathology of several autoimmune diseases including Graves disease, type I diabetes and rheumatoid arthritis." (PMID 28819312, 2017). "HLA-DRB1 alleles contribute to the development of autoimmune diseases as well as the production of autoantibodies." (PMID 26807576, 2016). "On the other hand, studies have shown that HLA-DRB1 has significant associations with autoimmune diseases and regulatory factor X 4 (RFX4)." (PMID 25836258, 2015). "HLA-DRB1*0301 has been reported contribute to the genetic susceptibility of some autoimmune diseases such as type 1 diabetes and multiple sclerosis." (PMID 23139797, 2012). "HLA-DRB1 has been shown to be associated with many autoimmune diseases, however, the mechanism of the HLA-DRB1 causing IgAN is poorly understood." (PMID 22578019, 2012). "The top three ranked genes, HLA-G, TAP2 and HLA-DRB1, are implicated in autoimmune diseases, while TAP2 is associated with SNPs characteristic for MG." (PMID 18851734, 2008). "Besides the celiac disease, other autoimmune disorders have similar susceptibility HLA alleles to MN: a significant increase was noted in HLA-DRB1*03:01 and *15:01 alleles in systemic lupus erythematosus and in multiple sclerosis." (PMID 40943538, 2025). "Significant associations have been demonstrated between HLA-DRB1*03 and many autoimmune diseases (AIDs), including Graves’ disease and Graves’ orbitopathy, Hashimoto’s thyroiditis, Addison’s disease, myasthenia gravis, Guillain–Barré syndrome, and systemic lupus erythematosus (SLE)." (PMID 39768617, 2024). "Therefore, all these characteristics make these vectors a potential risk for the development of autoimmune diseases, including autoimmune hypophysitis, in genetically predisposed individuals (HLA-DRB1), as occurs in ASIA syndrome." (PMID 39044822, 2024). "Polymorphisms in the HLA-DRB1 gene may predispose to an altered immune response, increasing the risk of autoimmune diseases and an exaggerated response of the immune system to certain pathogens or vaccines, as in ASIA syndrome." (PMID 39044822, 2024). "In summary, Bf*F1 could be associated to autoimmune disease either by itself or together with HLA extended haplotypes containing HLA-DRB1*03:01 and Bf*F1." (PMID 37794053, 2023). "HLA-DRB1 locus has been widely associated with autoimmune diseases, including sarcoidosis." (PMID 35661780, 2022). "Associations between other positions within HLA-DRB1 and autoimmune disease have been reported." (PMID 35094092, 2022). "Thus, gene products coded by HLA-DRB1 alleles that are known to associate with autoimmune disease susceptibility versus protection activate, respectively, pro-inflammatory or anti-inflammatory pathways in an AP-independent fashion." (PMID 33510427, 2021). "Thus, autoimmune disease susceptibility or -protective HLA-DRB1 alleles were found to reciprocally modulate signaling pathways, which determined the efficiency of pro-inflammatory versus anti-inflammatory macrophage differentiation outcomes." (PMID 33510427, 2021). "HLA-DRB1 alleles have been associated with several autoimmune diseases." (PMID 34484204, 2021).
autoimmune disease (continued). "It has been reported that specific allelic combinations of HLA-DQA1, HLA-DQB1, and HLA-DRB1 genes influence autoimmune disease predisposition, and, furthermore, their expression levels may also correlate with causes of the disease." (PMID 32547543, 2020). "Nevertheless, these classical HLA alleles might exert other effects, and protection by HLA-DRB1*13:01 likely accounts for the unexpectedly lower frequency of other autoimmune diseases in early-onset vitiligo cases than in late-onset cases." (PMID 30674883, 2019). "Due to the association with autoimmune diseases and proven application in population genetics, we aimed to investigate alleles of the Class II Human Leukocyte Antigens (HLA-DRB1) in the Mexican Mestizo population with aortic aneurysms and determine possible associations with susceptibility." (PMID 31174489, 2019). "The 8.1 ancestral haplotype (AH8.1) include the classical HLA alleles HLA-B*08:01 and HLA-DRB1*03:01, and has been associated with a large number of autoimmune diseases, but the underlying mechanisms for this association are largely unknown." (PMID 26207384, 2015). "Given the consistent association of HLA-DRB1 alleles with different autoimmune diseases, we explored the idea that the same HLA-DRB1 alleles could be influencing several different autoimmune diseases." (PMID 26605347, 2015). "The finding of this study correlates with that of previous studies, which supports the association of HLA-DRB1 with KBD as well as the autoimmune disease hypothesis of KBD." (PMID 24776925, 2014). "HLA-DRB1 shared epitope (SE) acts as an immune-stimulatory ligand that can direct T cell differentiation toward Th17 cells (that are) implicated in the pathogenesis of autoimmune diseases, including RA." (PMID 22355377, 2012). "Notably, in a recent study we have demonstrated that HLA-DRB1 alleles known to protect against several autoimmune diseases encode a protective epitope at the cusp region, which activates anti-inflammatory signaling leading to transcriptional and functional modulatory effects." (PMID 35281038, 2022). "Indeed, many autoimmune diseases are associated with certain HLA-DRB1 alleles." (PMID 34484204, 2021). "Despite of the fact that the origin of autoimmunity in autism is unknown, immune related genes on major histocompatibility complex, which have been associated with some autoimmune diseases, may play a central role in the development of autoimmunity in autism (e.g., HLA-DRB1 and C4B null alleles)." (PMID 21513576, 2011). "Specifically, components of the human leukocyte antigens (HLA) class II encoded HLA-DRB1*03-DQA1*0501-DQB1*0201 and DRB1*04-DQA1*0301-DQB1*0302 haplotypes have been associated with various autoimmune diseases, including AAI." (PMID 39423205, 2024). "A similar mechanism has been postulated for the protective effect of HLA-DRB1*13 in autoimmune diseases." (PMID 39570638, 2024). "As with many autoimmune diseases, GCA susceptibility is related to specific human leukocyte antigen (HLA) class II, mainly HLA-DRB1*0401 and HLA-DRB1*0404." (PMID 38541126, 2024). "It is also noteworthy that one of the molecular networks that resulted from the functional analysis enclose HLA-DRB1 and HLA-DRB5 that have been confirmed implicated in MS and other autoimmune diseases as well as in AD and other NDs." (PMID 39325116, 2024). "Within this chromosome, HLA-DQA1, HLA-DRB6, HLA-DQA2, HLA-DQB2, HLA-DRB1, and HLA-DQB1-AS1 were notable for having causal associations among several autoimmune diseases." (PMID 39590325, 2024). "When speaking of genetic factors for ASIA and other autoimmune diseases, genes such as HLA-DRB1 and HLA DQB1, alongside PTPN22, take the spotlight of genetic susceptibility to ASIA." (PMID 36837564, 2023).
autoimmune disease (continued). "Gene set analysis of the 100 most significant genes in the DNAemia meta-analysis found significant enrichment of genes associated with autoimmune disease of skin and connective tissue (DOID:0060039: FDR = 0.02; TG, DSG1,DST, LAMA3, HLA-DRB1)." (PMID 38005904, 2023). "HLA-DRB1*0801 and HLA-DQA1*0401 are in strong LD with HLA-DQB1*0402 (P = 5.2 × 10−8) and have been associated with autoimmune disease, including type 1 diabetes and systemic lupus erythematosus." (PMID 36929174, 2023). "Of particular interest, HLA-DRB1*13 alleles are the protective alleles shared by multiple autoimmune diseases and it has already been observed that HLA-DRB1*13:02 confers protection against organ-specific autoimmune diseases and some infectious diseases." (PMID 33815474, 2021). "Extending these analyses towards more HLA-DRB1 molecules, but also HLA-DQ molecules, will help pave the way to novel therapies to autoimmune diseases." (PMID 31520135, 2019). "Thus, while rs145954018del is associated with extreme vitiligo risk and early disease onset, HLA-DRB1*13:01 might simultaneously confer relative protection from other autoimmune diseases, and thus might account for the reduced frequency of concomitant autoimmunity in early-onset vitiligo cases." (PMID 30674883, 2019). "HLA-DRB1*03:01 and HLA-DRB1*04:01 are both implicated in the pathogenesis of various autoimmune diseases in either a predisposing, neutral or protective manner." (PMID 31520135, 2019). "HLA-DRB1 and PTPN22 are genes involved in the immune response, which have been commonly associated with HT and other autoimmune disorders in the literature." (PMID 29931474, 2018). "For instance, prior studies have noted significant differences in MHC gene expression among individuals carrying autoimmune disease-associated alleles, such as the HLA-DRB1 shared epitope, compared with those without." (PMID 40600064, 2025). "Meanwhile, HLA-DRB1*01:01 is the most common allele among HLA II-restricted virus-specific T cell epitopes linked to infectious diseases, and HLA-DRB5*01:01 is the most common one linked to autoimmune diseases." (PMID 40649820, 2025). "An argument in favor of this latter mechanism is offered by the HLA-DRB1*13 allele, which is suspected to confer a protective role against six autoimmune diseases, including MG, by an optimization of the T cells’ negative selection." (PMID 39728756, 2024). "This study analyzed the detection and neutralization of anti-IFN-γ autoantibodies (auto-Abs) from 8,430 healthy individuals of the general population, 257 HLA-DRB1*15:02 or 16:02 carriers, 1,063 patients with autoimmune disease, and 497 patients with unexplained severe disease due to EM." (PMID 38470480, 2024). "On the other hand, HLA-DRB1*03:01 is an allele associated with many autoimmune diseases and is not specific to GO." (PMID 37372389, 2023). "In turn, minor criteria refer to the immune related aspects of the syndrome; these include anti-adjuvant antibodies, the development of autoimmune disorders, development of secondary disorders such as IBS, and genetic predisposition via certain HLA-antigens (HLA-DRB1, HLA-DQB1)." (PMID 36837564, 2023). "While related research indicated HLA-DRB1 is closely related to autoimmune diseases." (PMID 35358276, 2022). "Moreover, HLA-DRB1*08:02 carriers were more prone to having autoimmune diseases and/or autoantibodies, especially anti-SS-A and/or -SS-B antibodies, compared with non-carriers (p = 0.033 and 0.035, respectively)." (PMID 33436735, 2021). "The protective effect of the HLA-DRB1*13:01 allele is not exclusive to MG but has also been found to be negatively associated with a plethora of autoimmune diseases in Europeans, and Asians." (PMID 34163474, 2021). "Moreover, polymorphisms in the HLA-DRB1 and DQB1 genes are strongly associated with and often causative in numerous autoimmune diseases." (PMID 33936069, 2021).
autoimmune disease (continued). "In contrast, our findings indicate that HLA-B*08:01, HLA-DQB1*02:01, and HLA-DRB1*03:01 have modest protective effects in depression, indicating that these alleles do not harbor shared risk for autoimmune disease and depression." (PMID 31570195, 2020). "This may be explained by the protective effects on these autoimmune diseases of HLA-DRB1*13:01, which typically occurs on the background of the early-onset rs145954018del-rs9271597A haplotype." (PMID 30674883, 2019). "For instance, HLA-DRB1*15, the most well-established susceptibility allele for MS risk, and HLA-DRB1*13, which is negatively related with various autoimmune diseases, may confer protection against JCV29." (PMID 31719595, 2019). "However, HLA-DRB1*03 is well known to be associated with an increased risk of many autoimmune diseases, not exclusively with GD." (PMID 37841270, 2023). "However, the HLA-DRB1*15:01, reported to represent a risk allele in PSC, was found to be protective to all forms of paediatric autoimmune diseases in an ethnically similar population, suggesting that HLA polymorphisms are only a component of the complex etiopathogenesis of AIH, ASC and PSC." (PMID 36059527, 2022). "Interestingly, we found a novel negative association with HLA‐DRB1*11, suggesting a potential protective role of this allele, as already documented in other autoimmune diseases." (PMID 33547763, 2021). "Individually, both HLA-DRB1*13:01 (Plogistic = 0.004, OR = 0.71, 95% CI 0.56-0.90) and rs145954018del (Plogistic = 0.04, OR = 0.74, 95% CI: 0.55–0.98) showed significant protective association against non-vitiligo autoimmune diseases." (PMID 30674883, 2019). "For MS, in HLA-DRB1*15 bearing individuals, a lack of vitamin D during early life could allow auto reactive T cells to escape thymic deletion and thus increase autoimmune disease risk." (PMID 19197344, 2009). "While the history of autoimmune disease was considered as a protective factor for glioma development, previous study found increased frequency of HLA-DRB1*08:03 and HLA-DRB1*08:03-DQB1*06:01 in populations with autoimmune thyroid disease." (PMID 34882724, 2021). "As HLA-DR3 (both HLA-DRB1*03:01 and HLA-DRB3*02:02) has been shown to be involved in the pathogenesis of different autoimmune disease, gaining more insight into the peptidome presented by HLA-DR3 can extend the knowledge on how the HLA molecules participate in the induction." (PMID 31520135, 2019). "The most prominent genetic risk factors are alleles within the HLA class, particularly HLA-DRB1, while a large number of non-HLA genes (FLT3, IRF5, STA4) involved in autoimmune diseases are interlinked in a network that regulates IFN signalling and dendritic cell and T cell function." (PMID 40495344, 2025). "Therefore, miR-499 may regulate HLA-DRB1 via the RFX4 pathway and participate in the pathogenesis of autoimmune diseases." (PMID 25836258, 2015). "Accordingly, infected HLA-DRB1*03:01 or HLA-DRB3*01.01 positive individuals may develop high affinity anti-RGD motif antibodies that react with the RGD motif in the host proteins, like fibrinogen, thrombin or von Willebrand factor, affecting haemostasis or participating in autoimmune disorders." (PMID 37492575, 2023). "Further analyses using imputed HLA allele frequencies indicated that especially HLA genes HLA-A, HLA-DRB1, HLA-DRB4, HLA-DQA1, and HLA-DQB1 may play a role in endodontic infections independent of autoimmune diseases." (PMID 40701953, 2025).
multiple sclerosis (91 papers, 2005 to 2026). A progressive autoimmune disorder affecting the central nervous system resulting in demyelination. "The earliest genetic associations identified with multiple sclerosis (MS) were within the human leukocyte antigen (HLA) gene family—notably the HLA-DRB1*15:01 allele." (PMID 40426812, 2025). "The third most cited study, “HLA-DR2 Dose Effect on Susceptibility to Multiple Sclerosis and Influence on Disease Course”, found that individuals with two copies of HLA-DRB1*15:01 had a significantly higher MS risk and worse disease progression." (PMID 40134718, 2025). "Multiple sclerosis and myasthenia gravis have been associated with the HLA-DRB1*15:01 allele as a primary genetic risk factor." (PMID 41009363, 2025). "An association between the HLA-DRB1*1501 genotype and multiple sclerosis (MS) has been confirmed in several studies, including ours." (PMID 38540417, 2024). "Previous studies have evaluated the frequency of HLA-DRB1*0403, observing an association between the genetic variant and the risk of developing multiple sclerosis in different populations." (PMID 37834042, 2023). "The HLA-DRB1 gene in the major histocompatibility complex (MHC) region in chromosome 6p21 is the strongest genetic factor identified as influencing multiple sclerosis (MS) susceptibility." (PMID 38145128, 2023). "HLA-DRB1*15:01 (DR15) is the risk allele for multiple sclerosis (MS) and Goodpasture syndrome, while HLA-DRB1*01:01 is protective against these two diseases." (PMID 36672249, 2023). "Differential methylation encompassing exon 2 of HLA-DRB1*15:01 has been shown in monocytes to the mediate effect of the HLA-DRB1*15:01 allele on its expression and risk of multiple sclerosis." (PMID 33886574, 2021). "Here we use the example of HLA-DRB1*16:01, an allele previously associated with immune response in multiple sclerosis." (PMID 31844174, 2020). "For example, HLA-DRB1*1501-DQB1*0602 is the most susceptible haplotype for multiple sclerosis and HLA-DRB1*0301–DQB1*0201 is the most susceptible haplotype for type 1 diabetes." (PMID 30060490, 2018). "HLADRB1*1501 (rs3135388) genotype and allelic variants of patients with multiple sclerosis (MS) and healthy volunteers." (PMID 23840333, 2013). "In a recent article addressing the influence of CIITA and HLA-DRB1 in multiple sclerosis, a complex risk relationship between these loci is presented." (PMID 22461888, 2012). "Multiple sclerosis (MS) is a complex trait in which alleles at or near the class II loci HLA-DRB1 and HLA-DQB1 contribute significantly to genetic risk." (PMID 18606010, 2008). "Genotyping data from the multiple sclerosis associated HLA-DRB1 gene was available in the majority of cases and fathers." (PMID 18682780, 2008). "The major candidate region for multiple sclerosis susceptibility comprises alleles of two genes located 85 kb apart that show almost complete LD in all ethnic groups studied to date, namely HLA-DRB1*1501 and HLA-DRB5*0101." (PMID 18397301, 2008). "Variation in the HLA-C gene influences susceptibility to multiple sclerosis independently of any effect attributable to the nearby HLA-DRB1 gene." (PMID 17252545, 2007). "Variation in the major histocompatibility complex (MHC) on chromosome 6p21 is known to influence susceptibility to multiple sclerosis with the strongest effect originating from the HLA-DRB1 gene in the class II region." (PMID 17252545, 2007). "Notably, a large Swedish study reported a synergistic effect between head trauma and HLA-DRB1*15:01 on multiple sclerosis risk, supporting the concept that HLA genotype can modulate the autoimmune consequences of tissue injury." (PMID 41425584, 2025). "The one that exhibited high centrality were “multiple sclerosis,” “HLA,” “HLA-DRB1,” “HLA-DR,” “genotype,” “haplotype,” “genetic susceptibility,” “human,” and “DNA polymorphism,” serve as pivotal nodes that strengthen the framework of the research network within this scientific domain." (PMID 40134718, 2025).